INS (insulin)
Diseases named in the same sentence as INS in open-access papers (continued):
Sharing a sentence is not in itself a finding about the gene and the disease.
acromegaly (continued). "Our aim was to assess insulin sensitivity and insulin secretion in active acromegaly using an IVGTT and to compare DI in healthy adults and acromegalic patients with normal and abnormal glucose tolerance status." (PMID 31620090, 2019). "Surgical cure of acromegaly improves insulin sensitivity and lowers circulating glucose and insulin concentrations." (PMID 31417493, 2019). "In all instances, biochemical control of acromegaly reverses this picture, increasing total fat mass and reducing lean body mass, while improving insulin sensitivity." (PMID 31417493, 2019). "Compared to SSA treatment, PEGV appears to be superior in improving glycemic control during the treatment of acromegaly patients, and it has been shown to improve peripheral and hepatic insulin sensitivity in acromegaly." (PMID 30474822, 2019). "Studies done in the past have demonstrated unequivocal evidence of reduced insulin senstivity in patients of acromegaly." (PMID 30948746, 2019). "In patients with acromegaly, improvement of disease control under pasireotide increases insulin sensitivity, but the concomitant impairment of beta-cell function is the main player determining the deterioration of glucose metabolism." (PMID 31417493, 2019). "A Polish study involving 239 acromegaly patients documented a significant improvement in glucose homeostasis and insulin sensitivity after TNS surgery." (PMID 30034367, 2018). "SST analogues administered in the context of acromegaly seem to inhibit GH release, with favourable changes in plasma lipids, and improvement of insulin sensitivity." (PMID 30053852, 2018). "In conclusion, the impact of SSA on the change in glucose metabolic status, insulin resistance, and β-cell function depends on the pretreatment glucose metabolism status in patients with acromegaly." (PMID 29853879, 2018). "Conversely, in acromegaly GH excess has a significant impact on adipose tissue and a detrimental effect on glucose metabolism and insulin signaling both at the hepatic and extrahepatic levels." (PMID 30662461, 2018). "A study performed in 12 acromegaly patients receiving long-term bromocriptine treatment showed a significant decrement in basal and glucose-stimulated insulin levels." (PMID 30034367, 2018). "Treatment of acromegaly, including medical treatment with pegvisomant, improves insulin sensitivity and glucose metabolism." (PMID 28713554, 2017). "A phase 4 study is currently ongoing that will evaluate the effects of incretin-based therapy compared with insulin on glycemic control at 16 weeks in patients with CD or acromegaly (ClinicalTrials.gov identifier NCT02060383)." (PMID 27405306, 2016). "T2DM develops in around 15% of patients with acromegaly, and adolescent individuals are more insulin resistant than either adults or pre-pubertal children." (PMID 24616775, 2013). "On the other hand, the participants with previous acromegaly exhibited severe impairment of dynamic insulin secretion." (PMID 19093000, 2008). "This study is consistent with previous reports showing that whole-body insulin sensitivity is normal after cure of acromegaly." (PMID 19093000, 2008). "Humans with a history of acromegaly exhibit reduced insulin secretion, muscular ATP synthesis and oxidative capacity but elevated liver fat content." (PMID 19093000, 2008). "Humans with a history of acromegaly exhibit normal whole body insulin sensitivity despite impaired ß cell function." (PMID 19093000, 2008). "As growth hormone (GH) excess can reduce insulin sensitivity, we examined the impact of previous acromegaly (AM) on glucose metabolism, lipid storage and muscular ATP turnover." (PMID 19093000, 2008). "This hypothesis could be explained by the existence of insulin resistance and enhanced lipolysis in acromegaly, which alter the availability of FAs for ceramide synthesis within sphingolipid metabolism." (PMID 41596725, 2026). "Another study confirmed lower intrahepatic lipids but higher fasting insulin in active acromegaly." (PMID 40725515, 2025).
acromegaly (continued). "Disease states of GH excess (e.g., acromegaly) and GH deficiency (e.g., congenital isolated GH deficiency) are characterized by increased and decreased GH, IGF-I and insulin levels, respectively, where the GH/IGF-I relationship is reflected by a “primary association”." (PMID 39665021, 2024). "This could account for the predominance of GH diabetogenic effects over IGF-1 insulin-sensitizing effects in acromegaly patients." (PMID 39331882, 2024). "In total, 53.7% of participants with acromegaly and 74.6% of participants with Cushing’s disease received antihyperglycemic medication during the pre-randomization phase, mostly metformin, either alone or in addition to insulin received from baseline." (PMID 38577574, 2024). "Interestingly, HOMA-IR decreases as early as 9 days postoperatively, reflecting exclusively the previous effect of acromegaly in insulin sensitivity." (PMID 36882643, 2023). "Therefore, DM can persist in patients with acromegaly, even after surgical remission, due to the irreversible change in insulin secretion and sensitivity." (PMID 35355553, 2022). "Nine patients were excluded from the primary analysis because of study discontinuation (n = 2; both with Cushing’s disease, randomized to insulin) or receipt of rescue medication (n = 7 [Cushing’s disease, n = 5; acromegaly, n = 2]) within 8 weeks of randomization." (PMID 34275099, 2021). "Similar studies from Mayo Clinic also found that insulin secretion was increased basally and after glucose loading in acromegaly." (PMID 34917145, 2021). "Metabolic effects of insulin and alterations in Cushing‘s disease and acromegaly." (PMID 33995272, 2021). "However, our study showed a compensatory upregulation of insulin secretion in newly diagnosed acromegaly with NGT." (PMID 34917145, 2021). "It is important to note that in patients with impaired GH secretion, both in acromegaly and in GH deficiency, insulin sensitivity is impaired, and this is not related to fat accumulations in any way." (PMID 33586392, 2021). "However, patients with acromegaly showed significantly elevated serum insulin levels, HOMA-IR and QUICKI values, compared with the other group." (PMID 33019423, 2020). "Reduction of insulin sensitivity (Si) has been widely demonstrated in active acromegaly." (PMID 31620090, 2019). "Reduced insulin secretion is also involved in the IGT of patients with acromegaly." (PMID 31620090, 2019). "Disruption in the glucose-insulin homeostasis is frequently present in patients of acromegaly." (PMID 30948746, 2019). "Medical treatment modalities for acromegaly may in turn reduce insulin resistance and increase insulin sensitivity." (PMID 30474822, 2019). "Decreased IR and β-cell functions and increased insulin sensitivity will be obtained in most patients after surgery regardless of their preoperative glucose tolerance status or whether they achieved acromegaly remission." (PMID 31736874, 2019). "However, the number of studies addressing insulin secretion in acromegaly is significantly lower than those assessing Si due to methodological issues." (PMID 31620090, 2019). "Indeed, the dysfunction of visceral fat, rather than the total amount, plays a relevant role in determining insulin resistance and impairment of glucose metabolism in patients with acromegaly." (PMID 30034367, 2018). "Therefore, the impairment of pancreatic β-cell function with the consequent reduction of insulin secretion significantly contributes to glucose metabolism derangement in insulin-resistant acromegaly patients." (PMID 30034367, 2018). "GH excess affects insulin sensitivity and gluconeogenesis and can alter pancreatic β-cell function, leading to a derangement of glucose metabolism in a considerable percentage of acromegaly patients." (PMID 30034367, 2018).
acromegaly (continued). "The authors ascribed the acromegaly-dependent insulin resistance to two counteracting factors: the GH-mediated lipolysis, determining an increase in free fatty acids, and a simultaneous compensatory mechanism performed by adiponectin, enhancing insulin sensitivity." (PMID 29036907, 2017). "Patients with acromegaly had higher glucose, higher insulin levels and higher HOMA-IR score." (PMID 26087292, 2015). "Our results might have additional impact on the judgment of insulin sensitivity in subjects under suspicion of acromegaly." (PMID 25517727, 2014). "Similarly to SST, it has also been reported an inhibitory action of CORT on insulin release in patients with acromegaly or prolactinoma." (PMID 23162532, 2012). "In addition, the medications employed in treating acromegaly may directly affect insulin sensitivity or secretion." (PMID 39119396, 2024). "Furthermore, the medications used in treatment of acromegaly may affect insulin sensitivity or secretion per se." (PMID 36882643, 2023). "Although some studies have described the glucose profile, beta-cell function, and insulin sensitivity in patients with acromegaly, most of them enrolled the GH patients under antidiabetic medicine which may interfere beta-cell function and insulin sensitivity analysis." (PMID 34917145, 2021). "Since the physiological reciprocal temporal pattern of GH and insulin is abolished in active acromegaly, where the continous GH elevation chronically activates intracellular GH signaling, it remains possible that this could impair insulin signaling, hence causing insulin resistance." (PMID 31417493, 2019). "Lowering GH levels improves glycemic control and increases insulin sensitivity in acromegaly; however, SRL therapy may exert variable effects on glucose metabolism, with worsening due to inhibition of insulin secretion and improvement due to improved insulin sensitivity with acromegaly control." (PMID 29767287, 2018). "In this article, we try to understand the effects of acromegaly on glucose homeostasis and the relationship between GH, IGF-1, and insulin signaling." (PMID 39119396, 2024). "Poor glycemic control has challenged acromegaly diagnosis due to low/normal IGF-1 level in 2 case studies; similarly to “wild-type” T2DM, IGF-1 also increases post insulin-treatment in secondary DM." (PMID 36882643, 2023). "In acromegaly there is a decrease in fat mass with worsening insulin sensitivity and mice with isolated GHD are characterized by greater insulin sensitivity despite excess fat mass." (PMID 31939483, 2019). "In patients with acromegaly and NGT the insulin levels followed a similar curve but were significantly higher than in controls between 2 and 90 min." (PMID 31620090, 2019). "Insulin sensitivity was significantly reduced in NGT patients, confirming previous studies on patients with active acromegaly." (PMID 31620090, 2019). "Moreover, patients with CD who were randomized to the incretin or insulin arm had higher FPG and HbA1c levels than those with acromegaly." (PMID 39735646, 2024). "Clinical data from patients with acromegaly indicate a negative correlation between intramyocellular lipid and insulin sensitivity." (PMID 36882643, 2023). "Insulin and IGF-1 serum levels may be elevated in the course of many endocrine disorders, including acromegaly, hyperprolactinemia, hypercortisolism, or congenital adrenal hyperplasia." (PMID 37626790, 2023). "Indeed, patients with acromegaly and NGT demonstrate higher homeostasis model assessment of beta cell function (HOMA-β) and insulin response to glucose and arginine than those with prediabetes/DM." (PMID 36882643, 2023). "GHR antagonists (GHRA) induce an improvement in acromegaly glycemic control through the decrease of glucose and the normalization of insulin secretion." (PMID 35448486, 2022). "IGF-1’s insulin agonism may partially offset those of GH, but circulating IGF-1 has a little role in regulating glucose homeostasis in acromegaly." (PMID 36176462, 2022).
acromegaly (continued). "Neither were suspected to be related to pasireotide; one patient with Cushing’s disease in the insulin at entry group died from febrile neutropenia, and one acromegaly patient in the no OAD group died from a subdural hematoma." (PMID 34275099, 2021). "Secondly, lacking information like body fat distribution, insulin sensitivity, and so on, it was hard to fully understand the decrease of serum asprosin levels in acromegaly patients." (PMID 33414826, 2020). "Patients with acromegaly and abnormal glucose tolerance had very different profiles ranging from almost no insulin release in response to increased glucose levels to very high insulin levels with no progressive decrease." (PMID 31620090, 2019). "Chronic GH excess induces an equipoise insulin resistance in patients of acromegaly irrespective of their glycaemic status." (PMID 30948746, 2019). "Hyperglucagonemia in patients of acromegaly and the lack of appropriate suppression of glucagon in post-prandial states is an outcome of exaggerated α-cell response to glucose and impaired insulin-mediated inhibition of α-cell through its paracrine action." (PMID 30948746, 2019). "It is tempting to suggest that the cure of acromegaly would reverse IFG in the first patient (vigorous insulin response, higher than in NGT acromegaly) but not in the second one (slight insulin response, lower than in NGT acromegaly)." (PMID 31620090, 2019). "The incretin hormones strongly influence the glucose-insulin homeostasis, however they have not been explored extensively and little is known about their effect on carbohydrate metabolism in patients with acromegaly." (PMID 30948746, 2019). "In this study, we showed that active acromegaly is associated with high HSI, which significantly decreases after treatment with SRL in concomitance with an improvement in insulin sensitivity and regardless of disease control." (PMID 30662461, 2018). "Acromegaly patients, in contrast to diabetic non-acromegaly ones, generally have a low amount of visceral fat and insulin resistance is mainly related to GH/IGF-1 excess." (PMID 30034367, 2018). "Through screening in rodents, analogs were identified with potent GH-suppressing activity with acceptably low insulin-suppressing activity, including the two SRIF analogs still most widely used clinically for treatment of acromegaly and NETs, octreotide (Sandostatin) and lanreotide (Somatuline)." (PMID 30232095, 2018). "Acromegaly is characterized by changes in concentrations and actions of GH, IGF-1 and insulin." (PMID 27568329, 2017). "Unlike SAs, which inhibit not only GH but also insulin secretion, pegvisomant normalizes IGF1 levels in most patients with acromegaly and has beneficial effects on glucose metabolism because it does not modify insulin secretion." (PMID 26429918, 2015). "This stage is reversible if adequate acromegaly therapy is introduced but later it will progress to a maximal beta pancreatic cells fasting response without further insulin enhance which is considered irreversible despite treatment." (PMID 26361517, 2015). "The participants were first grouped according to presence or absence of acromegaly, and then further divided into insulin-sensitive and -resistant subgroups." (PMID 25517727, 2014). "APolish study in 220 treatment-naïve patients with acromegaly reported nosignificant differences in basal plasma GH, IGF1 or fasting insulin concentrationsbetween normoglycaemic patients and those with impairments in glucose tolerance, although the latter group of patients wassignificantly older." (PMID 24692509, 2014). "Insulin sensitivity was increased, while β-cell function and IR were decreased in most patients after surgery, regardless of whether their acromegaly achieved remission." (PMID 31736874, 2019).
acromegaly (continued). "Afterwards, in terms of disease control in acromegaly, IR and β-cell functions decreased and insulin sensitivity increased after surgery regardless of whether acromegaly remission was achieved, which has also been reported in other studies." (PMID 31736874, 2019). "In the light of the discussion to lower the cut-off-value for the diagnosis of active acromegaly, e.g. to 0.4 ng/mL, it cannot be ruled out that in very highly insulin sensitive persons, high GH concentrations at fasting would not fall below the currently defined threshold during the OGTT." (PMID 25517727, 2014). "Thus, it is not surprising that whole-body insulin sensitivity was not impaired in these patients with a history of acromegaly." (PMID 19093000, 2008). "To date, only one study investigated the impact of PAS on β-cell function in patients with acromegaly, demonstrating that the worsening of glucose homeostasis is mainly ascribable to a decrease in insulin secretion, without a substantial impact on insulin sensitivity." (PMID 38532073, 2024). "Since, in parallel with people suffering from DM, endogenous insulin concentrations can be low in feline DM, a low IGF-1 reading could be obtained when sampling takes place prior to initiation of exogenous insulin treatment despite the presence of excess growth hormone due to acromegaly." (PMID 26023776, 2015). "Acromegaly patients in the non-randomized no OAD and OAD groups maintained mean HbA1c < 6.5% and FPG < 126 mg/dL with pasireotide treatment, whereas in the insulin at entry group, mean HbA1c and FPG levels were elevated at baseline and remained > 6.5% and > 126 mg/dL, respectively, over time." (PMID 34275099, 2021). "However in a recent study performed in non-acromegaly patients with type 1 DM, PEG treatment increased hepatic insulin-sensitivity, without significant changes in FFA." (PMID 30034367, 2018).